GSTA5 (glutathione S-transferase alpha 5)
Tractability: No criterion of Open Targets' tractability assessment is met for any kind of drug.
Gene: Protein-coding gene on chromosome 6 (52,831,655 to 52,840,843, reverse strand). Ensembl gene ENSG00000182793.
Subcellular location: Cytoplasm
Subcellular location (Human Protein Atlas): Cytosol
Pathways (Reactome):
Metabolism: Glutathione conjugation
Gene Ontology:
Molecular function: protein binding; glutathione transferase activity
Biological process: glutathione metabolic process; xenobiotic metabolic process
Cellular component: extracellular exosome; cytosol; cytoplasm
Genetic constraint (gnomAD): Loss-of-function variants: 21 observed, 19.6 expected, observed/expected ratio (o/e) 1.07, 90% interval 0.76 to 1.54. The upper end of that interval is the gene's LOEUF score, 1.54, which puts it in group 6 of 6, group 1 being the genes least tolerant of losing a copy. Missense variants: 307 observed, 247.94 expected, observed/expected ratio (o/e) 1.24, 90% interval 1.13 to 1.36. Synonymous variants: 96 observed, 86.84 expected, observed/expected ratio (o/e) 1.11, 90% interval 0.94 to 1.31.
Homologues: Orthologues: chimpanzee GSTA5 (96% identical), rabbit GSTA5 (77% identical), mouse Gsta3 (73% identical), rat Gsta1 (71% identical), rat Gsta3 (62% identical), zebrafish gstp1.1 (30% identical), tropical clawed frog gstp1 (27% identical), Caenorhabditis elegans gst-39 (26% identical), Caenorhabditis elegans gst-29 (25% identical), Caenorhabditis elegans gst-3 (25% identical), Caenorhabditis elegans gst-32 (25% identical), Caenorhabditis elegans gst-37 (25% identical), and 34 more. Paralogues in human: GSTA1 (90% identical), GSTA2 (89% identical), GSTA3 (86% identical), GSTA4 (53% identical), GSTP1 (29% identical), GSTM2 (26% identical), GSTM1 (24% identical), GSTM3 (24% identical), GSTM4 (23% identical), GSTM5 (22% identical), HPGDS (20% identical).
Diseases named in the same sentence as GSTA5 in open-access papers:
GSTA5 is named in the same sentence as 10 diseases in open-access papers, as found by Europe PMC text mining. Sharing a sentence is not in itself a finding about the gene and the disease. The quoted sentences say what the papers report.
lung carcinoma (3 papers, 2013 to 2023). "Co-culturing breast or lung cancer cells with astrocytes led to upregulated survival genes, including GSTA5, BCL2L1 and TWIST1, in tumor cells." (PMID 23426399, 2013). "Analysis of 15 GST isoforms of human lung cancer using the TCGA dataset showed GSTP1, GSTA2, GSTA5, GSTO2, and GSTZ1 were significantly upregulated in LUAD compared to corresponding normal tissues, suggesting their potential oncogenic effects on LUAD." (PMID 36709476, 2023).
breast carcinoma (2 papers, 2014 to 2023). "These authors also showed that co-culture of human MDA-MB-231 breast cancer cells with murine astrocytes protected the cancer cells from apoptosis by vincristine through upregulation of the anti-apoptotic survival genes, BCL2L1, TWIST1, and GSTA5." (PMID 25566497, 2014).
alcohol dependence (1 paper, 2024). Physical and psychological dependence on alcohol. "Studies on the relationship between GSTA5 and alcohol dependence are lacking." (PMID 38832034, 2024).
viral infection (1 paper, 2024). "The upregulation of genes, like SERPINA3 and GSTA5, points to a defensive response by the host to mitigate protease activity and oxidative stress, which are likely induced by the viral infection." (PMID 39456924, 2024). "These terms suggest GSTA5’s role in the detoxification pathways, which may be activated in response to viral infection to handle the increased load of foreign molecules." (PMID 39456924, 2024).
tumor (3 papers, 2013 to 2021). "RAs within the tumor drive upregulation of survival genes in tumor cells, in particular, GSTA5, BCL2L1, and TWIST1." (PMID 34859239, 2021).
infection (1 paper, 2024). The state of being infected such as from the introduction of a foreign agent such as serum, vaccine, antigenic substance or organism. "The importance of these results lies in the validation of TFF1, GSTA5, HSPA6, FOS, MPIG6B, F2 and HP not only as key markers for the presence of infection but also for their specificity in differentiating between various Mpox strains." (PMID 39456924, 2024).
GSTA5 also shares sentences with these, for which no sentence is quoted: cancer (4 papers); asthma (1); ciliopathies (1); diabetes (1).